LRP10 (LDL receptor related protein 10)
Description:
Probable receptor, which is involved in the internalization of lipophilic molecules and/or signal transduction. May be involved in the uptake of lipoprotein APOE in liver (By similarity).
Synonyms: LRP-10; MSTP087; DKFZP564C1940; MGC8675; LRP9; MST087
Tractability: Antibody: UniProt predicts a signal peptide or a membrane-spanning region; its Gene Ontology location is reachable by antibodies, with medium confidence. PROTAC: ubiquitination databases record sites on it.
Gene: Protein-coding gene on chromosome 14 (22,871,709 to 22,881,713, forward strand). Ensembl gene ENSG00000197324.
Subcellular location: Membrane; Membrane, coated pit
Subcellular location (Human Protein Atlas): Nucleoplasm; Nucleoli
Pathways (Reactome):
Sensory Perception: Retinoid metabolism and transport
Gene Ontology:
Molecular function: protein binding; low-density lipoprotein particle receptor activity
Biological process: vesicle-mediated transport
Cellular component: membrane; plasma membrane
Genetic constraint (gnomAD): Loss-of-function variants: 42 observed, 61.23 expected, observed/expected ratio (o/e) 0.69, 90% interval 0.54 to 0.89. The upper end of that interval is the gene's LOEUF score, 0.89, which puts it in group 3 of 6, group 1 being the genes least tolerant of losing a copy. Missense variants: 872 observed, 977.3 expected, observed/expected ratio (o/e) 0.89, 90% interval 0.84 to 0.94. Synonymous variants: 377 observed, 407.96 expected, observed/expected ratio (o/e) 0.92, 90% interval 0.85 to 1.01.
Homologues: Orthologues: chimpanzee LRP10 (99% identical), macaque LRP10 (98% identical), pig LRP10 (90% identical), rabbit LRP10 (90% identical), guinea pig LRP10 (88% identical), rat Lrp10 (88% identical), mouse Lrp10 (88% identical), dog LRP10 (80% identical), zebrafish lrp10 (40% identical), Drosophila melanogaster arr (8% identical). Paralogues in human: LRP12 (36% identical), LRP3 (36% identical), LRP1 (20% identical), LRP1B (19% identical), LRP2 (19% identical), VLDLR (16% identical), LRP8 (15% identical), NID1 (14% identical), NID2 (13% identical), LRP4 (12% identical), EGF (12% identical), and 2 more.